HOTTIP (HOXA distal transcript antisense RNA)
Diseases named in the same sentence as HOTTIP in open-access papers (continued):
Sharing a sentence is not in itself a finding about the gene and the disease.
cancer (continued). "MALAT1, HOTAIR, H19, HOTTIP, ANRIL, and NEAT1 are among the most famous lncRNAs which have been mostly studied in many types of cancer exhibiting dysregulation in cancer cells, tissues and body fluids of affected patients." (PMID 35281110, 2022). "Finally, six lncRNAs (DLEU2, HOTTIP, MALAT1, NEAT1, SNHG1, and TUG1), registered in Lnc2Cancer 2.0, a database offering comprehensive experimentally supported associations between lncRNA and human cancer, were selected as candidate lncRNAs for the diagnosis of HCC." (PMID 34185961, 2021). "For example, the lncRNAs TUG1, UCA1, SPRY4-IT1, HULC, HOTTIP, H19 and HOTAIR were found to be novel promising biomarkers for poor prognosis in human cancers." (PMID 29308050, 2018). "Several lncRNAs, such as HULC, HOTAIR, HOTTIP, GAS5, and HOST2, have been identified as miRNA targets in various cancers, and these findings provide further understanding of lncRNA regulation during tumorigenesis." (PMID 28492554, 2017). "The XLOC_006390, HOTTIP-005, and RP11-567G11.1 expression levels in the cancer tissues were all significantly higher than that in the non-tumorous tissues." (PMID 26447755, 2015). "A key limitation of our study is the absence of HOTTIP expression data in cancer versus control samples." (PMID 40959107, 2025). "Flow cytometry analysis showed that HOTTIP overexpression triggered the apoptosis of cancer cells; however, its knockdown had no influence." (PMID 35210436, 2022). "The results obtained indicated that elevated HOTTIP and HAGLR expression levels could predict poor prognosis in cancer patients, suggesting that HOTTIP and HAGLR might serve as novel prognostic biomarkers for cancer." (PMID 34805277, 2021). "HOTTIP, which lies at the 5’ tip of the HOXA locus and drives gene transcription by binding to the WD repeat domain 5 (WDR5)/mixed lineage leukemia (MLL) complex, has been identified as a critical factor with tumor progression in different cancers." (PMID 29415429, 2018). "The relationship between HOTTIP expression and the OS of cancer patients was found to be of no significant heterogeneity (I2 = 0%, P = 0.92), and the fixed-effect model was therefore applied." (PMID 27806342, 2017). "As emerging stars in cancer biomarkers, more and more lncRNAs were identified, and some functioned as oncogenes, such as CCAT2, HOTTIP and TUG1, while some may be acted as tumor suppressor genes, such as MEG3, GAS5, ANRIL." (PMID 28977885, 2017). "In conclusion, this meta-analysis demonstrated that the higher expression level of HOTTIP is correlated with positive LNM and poor OS in different types of cancer and HOTTIP might serve as a novel predictor of LNM and survival in human cancer." (PMID 27806342, 2017). "Given that the physical distance between LNCRNA-HIT, HOXA13, and HOTTIP is only 6.5 kb in both humans and mice, it is possible that LNCRNA-HIT’s function may also be co-opted in these cancers." (PMID 26633036, 2015). "Furthermore, we also observed a positive correlation between HOTTIP and HOXA13 expression levels both in cancer cell lines and clinical samples." (PMID 25889214, 2015). "Thus, in order to clarify regulation, significance, and usefulness of HOTTIP for both cancer and non-cancer diseases; to fill the identified research gaps; and to collectively prepare a comprehensive study to aid in better treatment outcomes, we carried out this updated review." (PMID 40616679, 2025). "As XLOC_006390, HOTTIP-005, and RP11-567G11.1 were the three most upregulated lncRNAs in PC tissues, we detected their expression levels in 144 cancer tissues and the paired adjacent non-tumorous tissues using qRT-PCR." (PMID 26447755, 2015).
tumor (96 papers, 2015 to 2026). ": High HOTTIP levels are associated with aggressive tumor characteristics, including increased invasion and metastasis." (PMID 40616679, 2025). "Next, we analyzed the correlation between GLI2 and HOTTIP expression levels and found that, in all tumor patients, high GLI2 expression was associated with high HOTTIP expression." (PMID 40624028, 2025). "The results revealed that in early TNM stages, HOTTIP expression was associated with tumor differentiation and vascular invasion." (PMID 40624028, 2025). "The late-stage disease and the presence of remote tumor deposits have been linked with the amplified expression of HOTTIP in samples from osteosarcomas." (PMID 39015175, 2024). "Dysregulation of HOTTIP has been associated with tumor progression in HNSCC, likely by influencing the expression of HOXA genes and potentially impacting cell differentiation and development." (PMID 38522008, 2024). "Collectively, the mechanistic model was proposed to illustrate the underlying molecular mechanism of HOTTIP-mediated tumor growth." (PMID 38481876, 2024). "A knockdown of either HOXA9 or HOTTIP resulted in a significant loss of tumour-initiating potential." (PMID 37108193, 2023). "According to a research, higher expression levels of HOTTIP have been linked to more aggressive tumor characteristics, such as greater tumor sizes, lymph node metastases, and advanced stage." (PMID 38186456, 2023). "Collectively, these data demonstrated that HOTTIP was associated with tumor recurrence and poor survival in GC." (PMID 32457911, 2020). "Our previous study showed that HOTTIP was markedly upregulated in the serum of GC patients and positively associated with tumor invasion depth, advanced TNM stage, and poor overall survival." (PMID 32457911, 2020). "In recent studies, the aberrant role of HOXA13 in cancer is frequently associated with HOTTIP expression, suggesting that their interaction is strongly related to the modulation of tumor evolution and progression." (PMID 31137568, 2019). "In the present study, we demonstrate that HOTTIP is associated with SCLC tumor progression and disease outcome." (PMID 29041935, 2017). "Elevated HOTTIP levels have been seen in patients with bigger tumors (T3/T4) and in those who have not had sentinel lymph nodes removed because of axillary nodes presence, suggesting a potential association between HOTTIP expression and tumor growth and lymphatic dissemination." (PMID 38186456, 2023). "Similarly, lncRNA HOTTIP/HOXA13 expression was linked to tumor progression and therapeutic outcome in HCC patients." (PMID 36338699, 2022). "Higher expression of HOTTIP was associated with pathological grade, tumor size, and TNM stage." (PMID 33768092, 2021). "Additionally, the up-regulated expressions of lncRNA-HEIH and HOTTIP promoted tumor progression and significantly associated with tumor progression and disease outcome in HCC patients." (PMID 34660653, 2021). "In the present study, the SNP-SNP interaction of HOTAIR rs1899663 with HOTTIP rs1859168 was strongly associated with GC, which may be due to the destruction of these molecules that are thought to function as tumor suppressors." (PMID 33028884, 2020). "To determine whether HOTTIP expression in tumor tissues was associated with the clinical efficacy of mitomycin, we performed Kaplan-Meier survival analysis for patients in the two groups." (PMID 33585440, 2020). "We also found that HOTTIP levels in plasma and tumor tissues were associated with the response of CRC to mitomycin and might function as an independent indicator predicting the efficacy of mitomycin." (PMID 33585440, 2020). "In addition, HOTTIP levels have been associated with tumor pathological characteristics and patient prognostic outcomes." (PMID 28938659, 2017). "In addition, we found that increased HOTTIP levels were significantly and negatively associated with shorter OS times in tumor patients." (PMID 28938659, 2017).
tumor (continued). "In addition, we found that high HOTTIP expression was positively associated with poor tumor differentiation (OR = 1.55, 95% CI: 1.03–2.32, P = 0.036) and a poor clinical stage (OR = 3.28, 95% CI: 2.22–4.83, P < 0.001)." (PMID 28938659, 2017). "Taken together, our data revealed that HOTTIP was implicated in the progress of BC and it might act as a tumor oncogene." (PMID 28036281, 2017). "Although, the differences between the tumor expression levels of genes and exosomal levels could be different and may account for these observed differences, an exosomal study in GC showed high levels of expression of HOTTIP to be diagnostic of GC." (PMID 36831603, 2023). "However, if experimental funds are permitted, further studies will be required based on the syngeneic model that is more ideal to demonstrate anti-tumor immune response to explain the specific underlying mechanism by which HOTTIP/IL-6/PD-L1 network influences OS." (PMID 31533774, 2019). "Silencing HOTTIP using miR‐192 and miR‐204 led to a decrease in cell viability, suggesting the potential tumor‐promoting role of HOTTIP." (PMID 40567251, 2025). "For example, such integrative approaches can clarify HOTTIP’s dual role as an oncogene or tumor suppressor in a context-dependent manner." (PMID 40616679, 2025). "In HCC patients, HOTTIP upregulation is correlated with advanced tumor stages and a poorer prognosis." (PMID 40284466, 2025). "Specifically, F. nucleatum-infected GC cells were shown to secrete exosomes enriched in lncRNA HOTTIP, which promote tumor progression through the miR-885-3p/EphB2/PI3K/AKT axis." (PMID 40871411, 2025). "Ectopic HOTTIP expression resulted in significantly increased tumor volumes and weights, whereas HOTTIP knockout led to decreases in both tumor volumes and weights compared with those in the control groups." (PMID 40624028, 2025). "HOTTIP functions as a ceRNA by sponging miR-218, a tumor-suppressive miRNA that normally inhibits the expression of HMGA1, a protein involved in chromatin remodeling." (PMID 40781643, 2025). "Increased expression of HOTTIP has also been related to high mortality and is an autonomous prognostic indicator for overall survival in individuals with this tumor type." (PMID 39015175, 2024). "Additional in vivo assessment of this interactive axis identified a role for HOTTIP in PTC tumorigenesis—supported by a significant decrease in tumor volume when HOTTIP expression was transcriptionally repressed." (PMID 38785786, 2024). "HOTTIP itself is targeted by tumor suppressor miRNAs, miR-192, and miRNA-240, and this regulation was shown to interfere with glutaminolysis by glutaminase GLS1 in HepG2 and SMMC7721 cells." (PMID 38203767, 2024). "The further rescue study indicated that DKK1 overexpression significantly attenuated the HOTTIP-facilitated tumor cell growth and Wnt/β-catenin signaling activation." (PMID 38481876, 2024). "Finding the precise molecular processes through which HOTTIP influences tumor behavior can open the door to the creation of targeted medicines that are specifically suited to each patient's HOTTIP expression patterns." (PMID 38186456, 2023). "Renal cancer is marked with increased expression of HOTTIP, which also is an indicator of poor prognoses such as metastasis, increased tumor size, vascular invasion, and reduced overall survival rate." (PMID 36770654, 2023). "Numerous previous studies have exhibited that high HOTTIP expression was relevant to larger tumor size, poor differentiation, deeper invasion depth, positive lymph node metastasis, advanced TNM stage, and poor overall patient survival." (PMID 36405735, 2022). "The tumors stemming from HOTTIP-knockdown cells demonstrated a higher growth rate, more significant volumes and heavier tumor weights." (PMID 35210436, 2022). "Specifically, M1 exosomes and HOTTIP inhibited tumor cells’ progression while activating the innate immune system." (PMID 35210436, 2022).
tumor (continued). "Consistent with the in vitro studies, the HOTTIP-silenced tumor was mostly inhibited by the chemical drugs." (PMID 34290981, 2021). "In a previous work of our group, we showed that higher tumor HOTTIP levels correlated with shorter TTR and OS in early stage NSCLC patients." (PMID 34111710, 2021). "The EVs derived from HCT116Mito inhibited the response of xenografted CRC cells to mitomycin with increased HOTTIP expression in tumor tissues." (PMID 33585440, 2020). "Further, high level of HOTTIP was also correlated with tumor invasion depth (p < 0.001), lymph node metastasis (p = 0.0052), and TNM stage (p < 0.001) in GC." (PMID 32457911, 2020). "The HOTTIP overexpression group displayed larger tumor size and weight than those in the NC group, which was consistent with the in vitro observations." (PMID 32457911, 2020). "The pooled OR was 3.57 (95% CI 2.58-4.93, p < 0.0001), which revealed that patients with high HOTTIP expression in tumor tissues were more likely to lead to high clinical stage." (PMID 32566641, 2020). "The pooled OR was 2.61 (95% CI 1.91-3.58, p < 0.0001), which suggested that the elevated HOTTIP expression in tumor tissues was more prone to LNM." (PMID 32566641, 2020). "To evaluate the effect of HOTTIP on chemoresistance in vivo, we established a xenograft tumor model using SGC7901 cells transfected with pcDNA-HOTTIP in nude mice." (PMID 32457911, 2020). "The depletion of HOTTIP decreased the volume and weight of the xenograft tumours, compared to the shControl group." (PMID 32307830, 2020). "HOTTIP (HOXA transcript at the distal tip) is a tumor-related long non-coding RNA (lncRNA) located at the chromosomal locus 7p15.2." (PMID 32457911, 2020). "In recent years, some studies have tried to elucidate the real role of HOTTIP in tumor behaviors including: a survey that suppressed HOTTIP expression by siRNA and elucidated that tumor cell migration and invasion in vitro are inhibited." (PMID 32587834, 2019). "HOTTIP has been reported to contribute to oncogenesis and tumour metastasis, thus identified as an oncogenic lncRNA." (PMID 30548190, 2019). "This study implies that HOTTIP is somehow involved in tumor metastasis through down regulation of dickkopf WNT signaling pathway inhibitor 1 (DKK1) tumor suppressor gene." (PMID 32587834, 2019). "After subcutaneous injection for 17 days, the mean tumor volume for the HOTTIP knockdown group was markedly smaller than any other group." (PMID 29415429, 2018). "The results from these studies were collectively analyzed in three parallel meta-analyses, all of which clearly showed that the high expression of HOTTIP correlates with shorter overall survival, higher tumor grade and poor prognosis." (PMID 29495592, 2018). "Tumor growth was most significantly inhibited in mice following HOTTIP knockdown treatment in MCF-7 cells compared with any other group." (PMID 29415429, 2018). "In the present study, we analyzed HOTTIP expression levels of 86 PCa patients in tumor and adjacent normal tissue by real-time quantitative PCR (qPCR)." (PMID 29884766, 2018). "To identify the levels of HOTTIP in PCa, we used the qPCR assay to analyze the expression of HOTTIP in 86 pairs of PCa tumor tissues." (PMID 29884766, 2018). "For the first time, HOTTIP expression was found to be correlated with tumor progression and metastasis formation, as well as with overall patient survival, thus proposing HOTTIP as a possible prognostic factor for HCC." (PMID 29495592, 2018). "We also validate the tumor-promoting function of HOTTIP predicted to serve as miRNA sponge and positively regulate the expression of EZH1." (PMID 29041935, 2017). "We also found that that the expression of HOTTIP was positively correlated with tumor size, lymph node metastasis and clinical stage in BC." (PMID 28036281, 2017). "Tumor growth was most significantly inhibited in mice following HOTTIP knockdown treatment either in H146 cell or in H446AR cell compared with the NC groups." (PMID 29041935, 2017).
tumor (continued). "After subcutaneous injection for 15 days, the mean tumor volume for the NC groups were more and more markedly larger than their HOTTIP knockdown treating groups, respectively." (PMID 29041935, 2017). "Overall, high HOTTIP expression levels were positively correlated with tumor size, lymph node status and TNM stage (P=0.025, 0.009, 0.0001, respectively)." (PMID 28036281, 2017). "The authors observed that the over-expression of HOTTIP is correlated with advanced pathological stage and larger tumor size." (PMID 27148353, 2016). "Tumor growth was inhibited in nude mice treated with gemcitabine alone (n = 4) or following HOTTIP-knockdown (n = 4) compared with the controls (n = 4)." (PMID 25889214, 2015). "As a crucial tumor promoter, HOTTIP promotes cell proliferation, invasion, and chemoresistance by modulating HOXA13." (PMID 25889214, 2015). "Tumor growth rate was most significantly inhibited in mice following combined gemcitabine treatment and HOTTIP knockdown." (PMID 25889214, 2015). "To determine relationship between HOTTIP and miR-192/-204 in vivo, we detected expression of miR-192, miR-204 and HOTTIP in 48 tumor-normal pairs." (PMID 26710269, 2015). "The ability of HOTTIP to confer chemoresistance in PDAC was further examined using an in vivo tumor model." (PMID 25889214, 2015). "Furthermore, lncRNA HOTTIP contributes to tumor growth while it inhibits cell apoptosis by downregulation of pro-apoptotic factor Bad and upregulation of anti-apoptotic factor Bcl-2." (PMID 40616679, 2025). "Together, these results suggest that HOTTIP promotes the growth of patient-derived tumor organoids." (PMID 40624028, 2025). "Furthermore, single-cell RNA sequencing analysis revealed significantly elevated HOTTIP expression in tumor epithelial cells, further supporting its protumorigenic role." (PMID 40624028, 2025). "Moreover, the exosome-mediated transfer of HOTTIP facilitates heterogeneity of tumor cells, further complicating treatment strategies and contributing to poor clinical outcomes." (PMID 40781643, 2025). "Furthermore, we monitored the HOTTIP/hnRNPA2B1/DKK1 regulatory axis in tumor specimens derived from nude mice." (PMID 38481876, 2024). "Moreover, the nude xenograft mice model demonstrated HOTTIP overexpression dramatically stimulated tumor growth in vivo." (PMID 38481876, 2024). "HOTTIP knock-out mice showed slower OC xenograft tumor growth in vivo." (PMID 37854681, 2023). "Intricate networks that can be used for therapeutic treatments may also be revealed by examining the interactions between HOTTIP and other molecular actors in the tumor microenvironment." (PMID 38186456, 2023). "We predicted that the high expression of HOTTIP with an approximate 12-fold change in ccRCC tumor tissues may promote tumor growth and a statistic shorter overall survival, which is consistent with previous studies." (PMID 36438902, 2022). "Taken together with those coming from cells lines, HOTTIP serves as a tumor suppressor in HNSCC." (PMID 35210436, 2022). "Interestingly, Yang and his colleagues also reported a positive correlation in BC between HOTTIP expression and lymph node metastasis, tumor size, and TNM staging." (PMID 34069089, 2021). "In vitro studies showed that down-regulation of HOTTIP expression could reduce the aggressiveness of tumor cells and increase their chemo-sensitivity." (PMID 34758879, 2021). "Therefore, the expression level of HOTTIP can be a predictor of tumor recurrence after LT in HCC patients." (PMID 34758879, 2021). "Taken together all this information we can speculate that tumor cells can modulate endothelial cell behavior in hipoxic conditions by releasing EV containing high levels of HOTTIP and this could enhance the metastasis process." (PMID 34111710, 2021).